SPP1 (secreted phosphoprotein 1)
Diseases named in the same sentence as SPP1 in open-access papers (continued):
Sharing a sentence is not in itself a finding about the gene and the disease.
cancer (continued). "SPP1+ macrophages are found in mesenteric lymph nodes with metastasis but not in mesenteric lymph nodes without metastasis, thus indicating that SPP1+ macrophages play a role in facilitating the expansion of disseminated cancer cells." (PMID 37480104, 2023). "Several studies have shown that the SPP1/CD44 axis contribute to cancer chemoresistance in solid cancers, so the SPP1/CD44 axis may represent one of the most critical mechanisms for cell-to-cell communication between cancer cells and TAMs." (PMID 37190178, 2023). "These evidences suggest that SPP1 plays a role in promoting the progression of various cancers." (PMID 36688087, 2023). "Receptor activation by SPP1 in immune cells affects cytokine production, immune cell differentiation and function, communication between the adaptive and innate immune system, and acts as an immune checkpoint to suppress the anti-cancer immune cell activity." (PMID 38264656, 2023). "Regarding prognostic biomarkers, we generated several gene signatures that embodied cancer hallmarks in various dimensions, including the malignant epithelial cell gene signature, tip cell gene signature, combined gene signature and SPP1/C1QC macrophage gene signature." (PMID 36725337, 2023). "SPP1 facilitated cancer cell chemoresistance via the activation of the CD44 receptor, PI3K/AKT signaling, and ATP-binding cassette (ABC) drug efflux transporter activity, and anti-SPP1 and anti-CD44 antibodies improved the sensitivity of cancer cells to cisplatin in a mouse model." (PMID 37190178, 2023). "Interestingly, the expression of SPP1 is highly regulated in invasive cancer cells, indicating its intriguing role in cancer progression and distant metastasis." (PMID 38067407, 2023). "Genetic variations in SPP1 are identified in the 5′ untranslated region (UTR), introns, exons, and 3′UTR sites and have been associated with individual susceptibility, development, and chronic inflammatory disease activity such as cancer." (PMID 36979437, 2023). "Among the dendritic cell subset markers of the monocyte-derived dendritic cells, it is noteworthy that CD1A mRNA counts were also found to be associated with the risk of relapse and cancer progression, while CD209 was associated only with an increase in SPP1 levels." (PMID 38275392, 2023). "On the basis of these findings, we hypothesized that chemotherapy enhances cancer-cell-derived GM-CSF expression, which activates TAM-derived SPP1 and, in turn, induces chemoresistance in cancer cells." (PMID 37190178, 2023). "The molecular changes in SPP1 were investigated using the cBioPortal for cancer genomics." (PMID 38067407, 2023). "In these hemorrhagic regions, we found an increased Cd68 signal, confirming macrophage infiltration, superimposed by upregulated expression of Hmox1 and Arg1, the latter of which is the archetypal marker for procancerous and immunosuppressive TAMs in mice, similar to CD163 and SPP1 in human cancers." (PMID 38060331, 2023). "In IHC analysis, SPP1 staining was stronger in TAMs than in cancer cells." (PMID 37190178, 2023). "SPP1+ macrophages played a complex role in multiple cancers." (PMID 37158834, 2023). "Furthermore, through functional enrichment analysis, we found a significant correlation between four signature genes (CBX2, LDHA, SPP1, and ZC4H2) and malignant tumor biology, exhibiting upregulation in high-risk patients." (PMID 37287752, 2023). "Thus, SPP1-related signals are considered to represent a potential target for anti-cancer immunotherapies." (PMID 37190178, 2023). "SPP1 is a secreted multifunctional phosphoprotein, also known as bone bridge protein-like protein or early T lymphocyte activation 1 protein, that specifically binds and activates matrix metalloproteinases (MMPs) in cancer." (PMID 36782138, 2023).
cancer (continued). "Prior studies suggest that polarization of macrophages toward this SPP1+ state is a result of TME properties, including oxygen tension, the presence of FAP+ cancer-associated fibroblasts, and ECM composition, consistent with our pathway analysis of SPP1+ macrophages." (PMID 38036590, 2023). "Remarkably, using this approach we found that interactions with carcinoma cells themselves are sufficient to instruct macrophages to induce pro-tumorigenic TAM identities and gene expression programs, including activation of a hallmark SPP1+ state." (PMID 38036590, 2023). "Here, using tumoroids and normal adjacent organoids from patients 8 and 24, we observe that CAFs have limited ability to induce SPP1+ macrophage polarization relative to carcinoma cells, and that the presence of both carcinoma cells and CAFs elicits the strongest SPP1+ macrophage polarization." (PMID 38036590, 2023). "However, most reports on SPP1 expression mechanisms have been related to the expression of SPP1 in cancer cells, and there have been few reports on SPP1 expression in macrophages." (PMID 36139536, 2022). "Osteopontin (OPN) previously known as Secreted phosphoprotein (Spp1) is a phosphorylated glycoprotein involved in homeostatic (biomineralization, wound healing, cell viability...) as well as pathological situations (cancer, inflammation, metabolic diseases...)." (PMID 36569860, 2022). "Pan-cancer analysis showed that SPP1 was in high expression in most of the 32 tumors." (PMID 36686660, 2022). "Therefore, to evaluate the SPP1 expression level on cancer cells and TAMs separately, double-IHC using macrophage markers was performed." (PMID 36139536, 2022). "As it is well-known that cancer cell-derived factors stimulate macrophage activation, we tested whether the CM of cancer cell lines influenced the SPP1 expression in monocyte-derived macrophages and THP-1 macrophages." (PMID 36139536, 2022). "SPP1 is a secreted arginine glycine aspartic acid containing phosphorylated glycoprotein overexpressed in various malignant neoplasms and it is reported to be involved in various functions, such as in cell adhesion and migration, apoptosis and bone calcification." (PMID 36585688, 2022). "SPP1 also promotes the expression of cancer stem cell markers such as OCT4 and SOX2." (PMID 35154316, 2022). "Deregulation of SPP1 has been identified in various cancers." (PMID 35154316, 2022). "The expression of SPP1 was significantly different in diverse human cancers." (PMID 35067176, 2022). "In addition, we investigated the relationship between SPP1 expression and clinical characteristics (pathological stage, histological grade, age, and gender) of 33 types of cancer." (PMID 35067176, 2022). "Further refinement of this matrix risk signature to specifically predict which lesions will progress to cancer identified a minimum 6-gene risk signature of RSPO1, CTHRC1, SPP1, MMRN1, COL10A1, and PRG4 as the most significant matrisomal predictors of premalignant progression with a ROC AUC of 0.99." (PMID 36404344, 2022). "Studies have also found that SPP1 could promote the proliferation, migration, and invasion of malignant tumor cells and inhibit cell apoptosis, leading to a poor prognosis in certain tumors." (PMID 35067176, 2022). "In many cases, the SPP1 expression level was higher on TAMs than on cancer cells." (PMID 36139536, 2022). "In addition, to further assess SPP1 expression levels in human cancers, we obtained the TGCA-derived transcriptome RNA-seq data of 33 cancers from the UCSC Xena database and analyzed the SPP1 expression using the R software." (PMID 35067176, 2022). "Increasing evidences indicate that SPP1 is an important prognostic biomarker for many cancers." (PMID 35067176, 2022). "Increasing evidence indicates that SPP1 is an oncogene in many cancers." (PMID 35067176, 2022). "Next, we examined whether the macrophage-derived SPP1 suppresses apoptosis of cancer cells under the administration of anticancer drugs." (PMID 36139536, 2022).
cancer (continued). "The EMT scores for the NETs/SPP1-high and -low groups were compared in each cancer type." (PMID 35432310, 2022). "Increased expression of SPP1 promoted invasion and metastasis in various malignant tumors." (PMID 35219893, 2022). "This study will contribute to a deeper understanding of the critical role of SPP1 in human cancers." (PMID 35067176, 2022). "The SPP1 gene has been reported to participate in cancer development and progression." (PMID 35790930, 2022). "By incorporating spatial transcriptomic data, we found a cluster of cells featured by high expression of PTN exhibited the highest m7G score and may communicate with adjacent cancer cells via SPP1 and PTN signaling pathways." (PMID 36036011, 2022). "Next, we examined whether the CM of macrophages and SPP1 would influence the re-growth of cancer cells pre-treated with PTX and PEM using a three-dimensional (3D) cell culture system." (PMID 36139536, 2022). "We speculated that SPP1 might be used as a potential prognostic and immune-related biomarker in human cancers." (PMID 35067176, 2022). "In addition, immunohistochemical assay results showed that SPP1 highly expressed in multiple types of cancer, including breast, colon, gastric, and liver." (PMID 35067176, 2022). "Secreted phosphoprotein 1 (SPP1) plays an essential role in various human cancers, but its role in radiation resistance remains unclear." (PMID 35593388, 2022). "As a highly specific osteolysis biomarker, SPP1 and type I collagen have been previously shown to be expressed and secreted by a variety of cancers, and participate in cell adhesion, bone resorption, cell adhesion, metastasis and other processes by binding to CD44 and integrin receptors." (PMID 36389722, 2022). "In line with several studies that have investigated the expression levels of SPP1 and OPN in different types of cancer in people, these findings might support the use of SPP1 or OPN expression as prognostic biomarkers in CAA and COSCC." (PMID 34493785, 2021). "Due to the role of ECM remodeling in cancer glycolysis, angiogenesis, and metastasis, we investigated the association between SPP1+ TAM signature, SPP1 expression with glycolysis, and EMT program, respectively, and found that there was a positive correlation between them in multiple cancer types." (PMID 34676217, 2021). "Data downloaded from TCGA and GTEx were used to analyze SPP1 expression in 33 types of cancer." (PMID 35058964, 2021). "Previous studies revealed that SPP1 is involved in the radiosensitivity of a variety of cancers." (PMID 34367279, 2021). "In pan-cancer analysis, we found that SPP1 was upregulated in most cancer types." (PMID 35058964, 2021). "Previously, SPP1 has been reported to be upregulated in many cancer types." (PMID 33996808, 2021). "Earlier studies reported that SPP1 could promote cancer progression through modulating the expression of VEGF and regulating ECM protein." (PMID 33850056, 2021). "SPP1 interacts with integrins to induce the activation of PI3K/AKT pathway in cancer cells." (PMID 34234236, 2021). "Overexpressed SPP1 expression had been confirmed in various types of cancers." (PMID 34126961, 2021). "Also, fibroblasts differentiated from bone marrow CD4+ monocytes enhance the cancer hepatocyte-like properties of LC cells through the secretion of SPP1 and activation of the PIK3K/AKT pathway." (PMID 34671675, 2021). "Several studies found increased SPP1 levels in different types of cancer." (PMID 33562105, 2021). "Besides, prognostic analysis indicated that a higher expression of SPP1 was found to be related to worse clinical outcome in six cancer types." (PMID 34676217, 2021). "In this report, we found SPP1 expression was higher in most of the human cancers." (PMID 33324676, 2020). "Clinical trials based on SPP1 are conducted for evaluating the prognostic outcome and treatment response of cancer, which may provide guidance for the development of promising therapies." (PMID 33324676, 2020).
cancer (continued). "Next, we used TIMER to investigate whether SPP1 level was related to the immunocyte infiltrating levels among four selected cancers." (PMID 33324676, 2020). "Next, we identified SPP1 correlated common genes in four selected cancers." (PMID 33324676, 2020). "Correlations between the expression level of BGLAP, SPARC, and SPP1 in different cancer types." (PMID 33240930, 2020). "It suggested that SPP1 may possess the characteristics of oncogenes or anti-oncogenes, which was determined by the cancer type." (PMID 33324676, 2020). "The distinct levels of SPP1 expression in these cancers may be due to different data collection methods, which need further verification." (PMID 33324676, 2020). "The high SPP1 expression facilitated the infiltration level of immune cells and their markers, further confirming the interactions between SPP1 and common genes and miRNA in cancers." (PMID 33324676, 2020). "Although SPP1 plays a role in many types of cancers, how its expression is regulated in relation to immune infiltration, gene mutation, gene and miRNA levels remains unclear." (PMID 33324676, 2020). "Additionally, using CIBER algorithm, the TIICs abundances and their correlation with SPP1 were assessed in four selected cancers based on gene expression profiles from TCGA." (PMID 33324676, 2020). "This study provided a deep insight into the functions of SPP1 in human cancer, which may provide guidance for the development of promising therapies." (PMID 33324676, 2020). "At the cell line level, NSCLC ranked ninth among cancer cell lines based on SPP1 expression." (PMID 32595698, 2020). "This indicated the vital part of SPP1 in these cancers by interacting with these genes and miRNAs." (PMID 33324676, 2020). "SPP1 is a multifunctional cytokine that affects cell proliferation, survival, drug resistance, invasion, and stem-like behaviour and promotes the invasion and metastatic progression of many carcinomas." (PMID 32503462, 2020). "Osteopontin (OPN, encoded by SPP1 gene), an integrin binding glycoprotein, has been implicated in a variety of physiological and pathophysiological processes, including bone remodeling, immune responses, and cancer progression." (PMID 30367545, 2019). "Meanwhile, SPP1 secreted by some types of cancers is likely less phosphorylated." (PMID 31879711, 2019). "Besides, many studies hold the opinion that SPP1 participates in the development and metastasis of malignant tumor." (PMID 30746900, 2019). "Our results suggest that SPP1 and SPP2 may be effective therapeutic or diagnostic targets in certain cancers." (PMID 31849319, 2019). "We found that in certain cancers SPP1 was over-expressed, while in others it was under-expressed, suggesting that depending on the particular cancer type SPP1 may be playing a pro- or anti-oncogneic function." (PMID 31849319, 2019). "SPP1 is phosphoprotein found upregulated in many cancers, including CRC." (PMID 30175151, 2018). "Elevated SPP1 levels have been detected in a variety of human cancers; it may serve as a potential prognostic factor in GC." (PMID 29921304, 2018). "The role of SPP1 in sphere-forming capacity of cancer stem cells is likely cell type dependent." (PMID 28030801, 2017). "In addition to the well-studied role of osteopontin in other cancers, the expression of SPP1 is regulated by Wnt signalling, one of the pathways that we identified as playing a role in the progression of benign plexiform neurofibromas to MPNSTs." (PMID 25884485, 2015). "Polymorphisms in the OPN gene, SPP1, may potentially alter the expression of OPN and then modulate the risk for cancer." (PMID 26267616, 2015). "Our results support the hypothesis that the deregulation of the CBX7/HMGA1b axis might contribute to cancer progression through the modulation of the SPP1 gene expression." (PMID 25595895, 2015).
cancer (continued). "We found that CBX7 negatively or positively regulates the expression of several genes (such as SPP1, SPINK1, STEAP1, and FOS, FOSB, EGR1, respectively) associated to cancer progression, by interacting with their promoter regions and modulating their transcriptional activity." (PMID 24865347, 2014). "Similarly, overexpression of Osteopontin (SPP1) has been found in a variety of cancers, including breast, lung, colorectal, stomach, ovarian cancers and melanoma." (PMID 21314937, 2011). "The fold change was highest (28.3) for SPP1 (osteopontin) that is one of the major extracellular matrix proteins in bone and is produced by numerous cell types including osteoblasts and osteoclasts, but also by NK cells, T cells, macrophages, and cancer cells." (PMID 22084725, 2011). "SPP1 (osteopontin), a secreted, integrin-binding glycoprotein with adhesive properties, has been shown to be correlated with metastasis to the bone and with poor prognosis in various cancers and is highly upregulated in all the metastatic samples in our study." (PMID 17430594, 2007). "Developing inhibitors or activators of SPP1 could open new avenues for cancer therapy." (PMID 41391064, 2025). "SPP1 might be vital for the cancer‐like characteristics of PAH." (PMID 41498045, 2025). "SPP1 macrophage polarization has been associated with negative clinical outcomes in cancer." (PMID 39639496, 2025). "Therefore, SPP1 may serve as a valuable prognostic biomarker and a potential target for cancer therapy in various solid tumors." (PMID 41391064, 2025). "Taken together, the communication network between cancer cells, T cells and vascular ECs, regulated by ligand‐receptor pairs representative of SPP1 signalling, may be an important mechanism responsible for bone metastasis and the poor prognosis of NSCLC patients." (PMID 39231761, 2025). "Additionally, SPP1 as a ligand could induce communications of pan T‐cell subtypes to cancer cells specifically in BM or to senescent cancer cells via adhesive receptors ITGAV_ITGB1, ITGAV_ITGB5 and ITGAV_ITGB6." (PMID 39231761, 2025). "In a pan-cancer study, Shen and colleagues delineated a neutrophil extracellular trap (NET) signature profile associated with inflammation, metastasis, and poor patient outcomes, among which, Spp1 emerged as one of the top NET-related genes contributing to malignancies." (PMID 40865052, 2025). "However, SPP1 may contribute to disease processes such as fibrosis, immune dysregulation, or cancer metastasis." (PMID 40559389, 2025). "However, cancer metastasis is a multistep cascade, and the function of SPP1 in distant organs and whether SPP1 regulates the PMN to fuel organ-specific metastasis of HCC is still unclear." (PMID 39529085, 2024). "In addition, frequent upregulation of SPP1 in cancer leads to poor prognosis and may be suitable as a therapeutic target for chemoradiotherapy resistance." (PMID 39796714, 2024). "The SPP1/CD44 axis has been linked to cancer chemoresistance in solid tumors, and it may represent a critical mechanism for cell-to-cell communication between cancer cells and TAMs53,54." (PMID 38521868, 2024). "Thus, SPP1 is thought to be a promising target for anti-cancer therapy." (PMID 37190178, 2023). "However, previous studies indicated that SPP1 regulates cancer cells’ proliferation and motility." (PMID 38067407, 2023). "Furthermore, tumorsphere numbers and sizes were markedly reduced in SPC-A1 after transfection with siRNA-2 and -3, indicating that SPP1 promoted cancer stemness and might be a potential target for CSCs." (PMID 37287976, 2023). "Taken together, these findings suggested an important role played by SPP1 cancer development and progression and prompted us to investigate the protein expression patterns and the prognostic value, as well as the molecular pathways and biological function of SPP1." (PMID 38067407, 2023). "Notably, in this study, we demonstrated that the SPP1 expression was related to cancer immunity." (PMID 35067176, 2022).